LEP (leptin)
Diseases named in the same sentence as LEP in open-access papers (continued):
Sharing a sentence is not in itself a finding about the gene and the disease.
thyroid cancer (continued). "In previous studies, the analysis of adiponectin and thyroid cancer mostly focused on TNF-, IL-6, Leptin and Adiponectin." (PMID 32819324, 2020). "The effects of leptin and OB3 on carbohydrate metabolism-related gene expression were variable in the thyroid cancer cell lines studied." (PMID 27050378, 2016). "Consistent evidence shows that in patients affected by thyroid cancer, the circulating levels of Acrp30 are deregulated compared to healthy controls, while the correlations between leptin and thyroid cancer are not clear." (PMID 33587254, 2021). "Unlike the parental peptide hormone, the OB3-leptin peptide did not stimulate cancer cell proliferation in cervical cancer HeLa cells or any thyroid cancer cells examined." (PMID 28750624, 2017). "In contrast to the parent peptide hormone, OB3-leptin peptide did not stimulate cancer cell proliferation in MTT assay in HeLa cells (data not shown) or in all of the thyroid cancer cells examined by us." (PMID 27050378, 2016). "In order to determine whether leptin and OB3 affect glucose metabolism-related gene expression in human thyroid cancer cells, we measured expression of glucose transporter (GLUT1, GLUT2, GLUT5) genes and the hexokinase 1 gene in a panel of cell lines." (PMID 27050378, 2016). "Thyrotropin (TSH) is a pituitary hormone that supports differentiated thyroid cancer; leptin, but not OB3, was found in the present studies to increase circulating TSH levels in intact mice." (PMID 27050378, 2016). "Leptin and OBR expression has also been studied in thyroid cancers." (PMID 23425972, 2013). "We found that Acrp30 treatment alone inhibits cell proliferation and cell viability in a time and dose-dependent manner; leptin alone does not influence thyroid cancer cells (BCPAP and K1) proliferation, but the combined treatment reverts Acrp30-induced effects on cell proliferation." (PMID 33587254, 2021). "However, our recent studies indicated that leptin does not stimulate the proliferation of different thyroid cancer cells." (PMID 28750624, 2017). "The effect of insulin on leptin expression in thyroid cancer has not been studied." (PMID 23425972, 2013). "Therefore, reduction or normalization of high leptin levels in thyroid cancer patients was not assessed." (PMID 22007338, 2011). "Thus, OB3 and leptin alter the expression of glucose metabolism-related genes in various types of thyroid cancer cells, but the actions of OB3 and leptin and patterns of genes affected are cell line-specific and may not related to cancer cell proliferation or invasiveness." (PMID 27050378, 2016). "The in vivo studies also proved that leptin, but not OB3, remarkably enhanced the levels of thyrotropin (TSH), a growth factor for thyroid cancer." (PMID 34356668, 2021). "In vivo studies in the mouse showed that leptin, but not OB3, significantly increased circulating levels of thyrotropin (TSH), a growth factor for thyroid cancer." (PMID 27050378, 2016). "On the other hand, papillary and follicular thyroid cancer cells exhibited no significant increase in the expression of genes involved in the invasion in response to OB3 and leptin." (PMID 27050378, 2016). "Likewise, Cheng and colleagues reported that the treatment with 125 ng/ml of leptin alone does not affect cell proliferation but increases migration of BCPAP and K1 thyroid cancer cells." (PMID 33587254, 2021). "The serum leptin levels did not rise, and the significant decrease in the leptin levels in WDTC patients were paradoxical, and therefore support the concept of a relationship between leptin and thyroid cancer, making leptin a possible etiologic factor in thyroid carcinogenesis." (PMID 24867470, 2014).
hypogonadism (38 papers, 2008 to 2025). A disorder characterized by decreased function of the gonads. "In severely obese patients, leptin and inflammatory cytokines inhibit kisspeptin, a GnRH release stimulator, potentially causing hypogonadism by impairing the hypothalamus–gonadotroph–gonadal axis, especially in those with leptin resistance." (PMID 39027638, 2024). "It has been shown that leptin is necessary for human reproduction since starvation-induced leptin suppression and genetic models of leptin deficiency are associated with hypogonadism due to hypothalamic GnRH deficiency." (PMID 36797524, 2023). "Leptin-deficient mice exhibit reduced gonadotropin-releasing hormone (GnRH) secretion, leading to gonadotropin deficiencies and hypogonadism." (PMID 35267914, 2022). "Increased leptin induces a “leptin resistance” response that may ultimately lead to functional hypogonadism due to testosterone deficiency." (PMID 40566611, 2025). "Leptin treatment corrects the hypogonadism of leptin-deficient ob/ob mice and starved normal mice, accelerates the onset of puberty in rodents and increasing leptin levels may signal the onset of puberty in boys and girls." (PMID 19017403, 2008). "Multiple factors contribute to secondary hypogonadism, including inflammatory mediators of low chronic inflammation, such as tumor necrosis factor and interleukin 1; insulin resistance; leptin resistance; and reduced kisspeptin secretion." (PMID 37479795, 2023). "Currently, the most widely accepted mechanism of diabesity-related hypogonadism is that insulin and leptin resistance diminishes the stimulatory function of kisspeptin neurons on the secretion of GnRH." (PMID 34177811, 2021). "Several factors are involved in the pathogenesis of this form of hypogonadism, in particular, a role of estradiol, insulin, leptin, and other pro-inflammatory cytokines has been proposed." (PMID 31817436, 2019). "While the absence of marked metabolic differences in these mice is in line with earlier studies, the hypogonadism observed in these mice are the first evidence of a divergent pathway of leptin to regulate metabolism and reproduction." (PMID 29905528, 2018). "Secondary hypogonadism might be due to inhibition of gonadotropin secretion through a mechanism such as leptin resistance or adipokine release as a result of the effect of the virus itself or comorbid conditions." (PMID 38476640, 2024). "An important role in the pathogenesis of functional secondary hypogonadism is played by the visceral adipose tissue, in which a variety of circulating mediators (including leptin and pro-cytokines) contributing to the suppression of the HPT axis at multiple levels is synthesized." (PMID 31817436, 2019). "In addition to effects of leptin, elevated corticosteroid levels, elevated insulin levels, and hypogonadism may be involved in bone metabolism in ZFR, either alone or in combination with abnormal leptin function." (PMID 36902744, 2023). "Together, these results indicate that adequate leptin signaling in both testes and neuronal circuits sustains the physiological activity of the HPT axis, and that the presence of leptin-resistance could favor the development of functional hypogonadism and the related reproductive dysfunction." (PMID 35897769, 2022). "Low BMD in AN is considered multifactorial and related to lower BMI, lower lean mass, hypogonadism, Growth Hormone resistance and low IGF-1, high cortisol levels, high PYY levels, and low levels of leptin, oxytocin, insulin and amylin." (PMID 37393263, 2023). "However, as for insulin and T2DM, the main link between leptin and hypogonadism could be represented by leptin resistance, leading to either defects in the intracellular signaling of the leptin receptor or an abnormal leptin transport across the blood–brain barrier." (PMID 31817436, 2019). "Mice lacking leptin (ob/ob, Lep gene) or leptin receptor (db/db, Lepr gene) are obese, infertile, and have hypogonadism, among other disturbances." (PMID 40276575, 2025).
vitamin D deficiency (37 papers, 2011 to 2025). A nutritional condition produced by a deficiency of VITAMIN D in the diet, insufficient production of vitamin D in the skin, inadequate absorption of vitamin D from the diet, or abnormal conversion of vitamin D to its bioactive metabolites. "In another study, high blood leptin and endothelin-1 levels, vitamin D deficiency, and food reward hormone dysregulation were found in normal weight children exposed to high concentrations of ambient PM2.5 in Mexico City." (PMID 39767974, 2024). "Previous experimental studies have linked antiangiogenic factors with other maternal serum parameters, such as vitamin D deficiency, increased IL-6 or C-reactive protein, and decreased leptin levels." (PMID 35631313, 2022). "Vitamin D deficiency, inhibition of serotonin and MT secretion, and increased secretion of leptin and kisspeptin are involved in the occurrence of PP." (PMID 36213197, 2022). "The results showed that treating vitamin D deficiency decreases the circulating leptin and adiponectin but doesn’t have a significant effect on LAR." (PMID 33680012, 2020). "Other biomarkers that were found to be associated with POD include BDNF, reduced cholinesterase activity, serum leptin, hypoalbuminaemia and vitamin D deficiency." (PMID 30797230, 2019). "Additionally, vitamin D deficiency elevates fatty acid synthase levels, reduces leptin concentrations, inhibits lipolysis, and facilitates lipid accumulation." (PMID 40521355, 2025). "Changes in cytokines (such as interleukin-1, interleukin-6, and tumor necrosis factor-α), adipokines (such as leptin and adiponectin), and calcium and vitamin D deficiency may also play a role in bone metabolism changes during weight loss." (PMID 39770498, 2024). "Researchers suggest that bariatric surgery may result in bone loss due to potential vitamin D deficiency, mechanical unloading from weight loss, and changed hormonal secretion such as reduced leptin and estrogen in perimenopausal women." (PMID 32326591, 2020). "In addition to altered mechanical proprieties, there are differences in the onset of puberty due to the vitamin D deficiency and the direct effects of adipokines, such as leptin." (PMID 32457859, 2020). "Thus, we aim to evaluate the effect of vitamin D deficiency or insufficiency treatment on serum adiponectin, leptin, and LAR in T2DM patients." (PMID 33680012, 2020). "It is suggested that vitamin D receptors in the adipocytes of the adipose tissue may regulate adipokine gene expression and vitamin D deficiency may be associated with increased leptin levels and decreased adiponectin levels." (PMID 32153911, 2018). "Leptin reached the most accurate AUCROC = 0.685; (p = 0.0291) for vitamin D deficiency prediction, with a cut-off value of 7.38 ng/mL with 79.5% sensitivity and 51.4% specificity." (PMID 36983369, 2023). "In current study, subjects with vitamin D deficiency and NAFLD had increased leptin value but lower HDL-C level." (PMID 31311491, 2019). "However, bariatric surgery may result in bone loss due to potential vitamin D deficiency, mechanical unloading from weight loss, and a change in hormonal secretion such as a reduction in leptin, and estrogen that may be more pronounced in women who may be perimenopausal." (PMID 31134746, 2019). "In addition, patients with vitamin D sufficiency also had higher serum levels of adiponectin (P = 0.003) and leptin / adiponectin ratio (P < 0.001) than patients with vitamin D insufficiency." (PMID 36071429, 2022). "Our study indicated that treating vitamin D deficiency or insufficiency has a significant effect on serum levels of leptin and adiponectin, but does not have a meaningful effect on LAR." (PMID 33680012, 2020). "Subjects with Vitamin D deficiency have significantly high values (p < 0.05) for BMI z-score, waist circumference, waist z-score, body fat percentage, FMI, systolic and diastolic BP, total cholesterol, triglycerides, LDL-C, insulin, HOMA-IR, leptin, and PTH." (PMID 32024097, 2020).
vitamin D deficiency (continued). "The relationships between the principal adipokines (leptin, adiponectin, resistin) are revealed in the presence of normal vitamin D content and in vitamin D deficiency." (PMID 30881343, 2019). "The hypothesis of this study was that H pylori infection and vitamin D deficiency induce inflammatory cytokines (HS-CRP) or adipokines (adiponectin, leptin), leading to the development of MS." (PMID 27149497, 2016). "The mean serum concentrations of leptin (P = 0.002), resistin (P = 0.037), and TNF-α (P < 0.001) were significantly higher in the cases with vitamin D insufficiency (cases) than those with vitamin D sufficiency (controls)." (PMID 36071429, 2022). "Those who recovered from vitamin D deficiency had a lower body fat percentage and lower serum leptin levels than those who did not recover from vitamin D deficiency, which suggests that there may be an association between adiposity and vitamin D levels mediated by leptin." (PMID 34830710, 2021).
gastric cancer (35 papers, 2013 to 2025). A primary or metastatic malignant neoplasm involving the stomach. "In patients with intestinal metaplasia (IM), the serum leptin concentration media was 116.6 pg/mL and, by multivariate analysis, it was found that leptin concentration is a risk factor for diagnosis of IM, which in turn serves to identify patients at risk of developing gastric cancer." (PMID 33334030, 2020). "Previous studies have reported lower levels of adiponectin and leptin in gastric cancer patients than controls." (PMID 37455285, 2023). "In gastric cancer, leptin increases the mRNA and protein levels of those EMT markers—Snail and N-cadherin—inducing EMT in such a manner." (PMID 37686525, 2023). "Previous reports indicated that the upregulation of STAT3/HK2 contributed to the activation of dendritic cells by leptin-induced glycolytic metabolism, and circular RNA circCUL3 eliciting the Warburg effect of gastric cancer." (PMID 36431990, 2022). "In human cancers, a high leptin level is involved in accelerating tumor growth, such as breast, pancreatic, colorectal, ovarian, lung, esophageal, and gastric cancers, in cell and in animal models." (PMID 35628510, 2022). "Studies have shown that leptin and its receptor (leprb) are independent factors for the poor prognosis of patients with gastric cancer and suggest that leptin-leperbis is a necessary factor for the action of antidepressants." (PMID 34491229, 2021). "Leptin was found to be overexpressed in the intestinal type of gastric cancer and in well-differentiated tumours." (PMID 34827598, 2021). "Both of these signaling axes were important for the leptin-induced proliferation of gastric cancer cells." (PMID 33334030, 2020). "In the MKN28 gastric cancer cell line, leptin treatment induced JAK2 and ERK1/2 activation through transactivation of the EGFR, which in turn seems to be dependent on the metalloproteinase-dependent release of EGFR ligands." (PMID 33334030, 2020). "In gastric cancer, leptin induces tyrosine phosphorylation of EGFR resulting in transactivation of this cascade." (PMID 30634942, 2019). "Studies have not only highlighted that leptin and its receptor (LepRb) are independent poor prognostic factors in gastric cancer (GC) patients but also shown that the leptin-LepRb is necessary for antidepressant-like behaviors." (PMID 28316984, 2017). "Leptin is a hormone derived from stomach as well as adipose tissue and gastric leptin is involved in the development of gastric cancer." (PMID 26839577, 2016). "Expression of leptin and leptin-receptor were observed in 37% (128/343) and 58% (198/343) of total gastric carcinomas, respectively." (PMID 26147886, 2015). "Leptin signaling-related proteins were commonly expressed in gastric carcinomas except for pSTAT3; pAkt positive in 79% (271/343) of gastric carcinomas, mTOR in 49% (169/33), HIF-1 alpha in 36% (123/343), ERK in 29% (101/343), and pSTAT3 in 8% (29/343)." (PMID 26147886, 2015). "In patients with more advanced gastric cancer, several factors including ghrelin, leptin, adiponectin and insulin-like growth factor -I (IGF-I) are involved in the cachexia." (PMID 24098650, 2013). "Based on public omics data, it was also found that some of these biomarkers showed significant changes in the progression from gastritis to dysplasia and gastric cancer, and were reported to participant in the progression of gastric cancer, such as LEP, CCL2, CD14 and TNF." (PMID 39367502, 2024). "Mechanistically, leptin can stimulate cell proliferation in gastric cancer cells, which may contribute to cancer development." (PMID 37455285, 2023). "However, studies of histological preparations in patients with IM and patients with gastric cancer report an increase in expression and levels of gastric leptin." (PMID 35712481, 2022).